ENSG00000268790 (novel protein)
Gene: Protein-coding gene on chromosome 19 (16,577,642 to 16,660,115, reverse strand). Ensembl gene ENSG00000268790.
Genetic constraint (gnomAD): Loss-of-function variants: 9 observed, 11.16 expected, observed/expected ratio (o/e) 0.81, 90% interval 0.49 to 1.4. Missense variants: 81 observed, 83.84 expected, observed/expected ratio (o/e) 0.97, 90% interval 0.81 to 1.16. Synonymous variants: 25 observed, 32.72 expected, observed/expected ratio (o/e) 0.76, 90% interval 0.56 to 1.07.